LRP1 (LDL receptor related protein 1)
Diseases named in the same sentence as LRP1 in open-access papers (continued):
Sharing a sentence is not in itself a finding about the gene and the disease.
acute respiratory distress syndrome (5 papers, 2017 to 2025). Progressive and life-threatening pulmonary distress in the absence of an underlying pulmonary condition, usually following major trauma or surgery. "Previously, plasma sLRP1 was shown to antagonize ligand endocytosis by cellular LRP1 in the lungs of patients with acute respiratory distress syndrome 19, preventing the cellular clearance of MMPs." (PMID 28557183, 2017).
bladder cancer (5 papers, 2023 to 2025). "LRP1 has also been shown to have predictive significance in metabolism-related genes in bladder cancer." (PMID 37124542, 2023).
COVID-19 (5 papers, 2022 to 2025). A disease caused by infection with severe acute respiratory syndrome coronavirus 2. "Particularly, this study reports upregulated ADA, BTC, DPP6, EDIL3, LIF, ENTPD2, Flt3L, and LRP1 in severe COVID-19 patients for the first time." (PMID 36428847, 2022). "This study demonstrates that LRP1 displays a bidirectional course in COVID-19." (PMID 37168200, 2023). "Furthermore, this study reports markers including ADA, BTC, DPP6, EDIL3, LIF, ENTPD2, Flt3L, and LRP1 to be upregulated in severe COVID-19 patients; hence, they are proposed as novel biomarkers for severe cases of COVID-19." (PMID 36428847, 2022). "Notably, monocyte LDL receptor-related protein (LRP1)/CD91 expression was significantly and selectively reduced in patients with severe COVID-19." (PMID 39136010, 2024). "In our series, the proportion of LRP1/CD91 expressing monocytes was reduced in severe cases and was inversely correlated with the level of CXCL10, selected as a representative cytokine in the storm observed in COVID-19 patient sera." (PMID 39136010, 2024).
leukemia (5 papers, 2019 to 2024). A malignant (clonal) hematologic disorder, involving hematopoietic stem cells and characterized by the presence of primitive or atypical myeloid or lymphoid cells in the bone marrow and the blood. "Membrane P3 (mP3) on acute myeloid leukemia (AML) blasts inhibits T cell proliferation through LRP1 and mP3 interaction, resulting in the evasion of anti-leukemia T cell immune response." (PMID 37020553, 2023). "In the present study, we demonstrated that induction of leukemia K562 cells with hemin, not only enhanced the autophagy pathway, but also activated overexpression of the LRP1 protein and gene." (PMID 30523204, 2019). "Recent research has linked the activation of the Notch pathway with the low-density-lipoprotein-receptor-related protein 1 (LRP1), and its inhibition may be explored as a potential target for leukemia management." (PMID 36672729, 2023). "A recent study on leukemia has demonstrated the critical role of LRP-1 on the NOTCH pathway." (PMID 36267880, 2022).
Marfan syndrome (5 papers, 2007 to 2023). A disorder of the connective tissue. "Consistent with the similar phenotype between Lrp1 deficiency and Marfan syndrome, a recent study showed that LRP1 also protects the vasculature by regulating matrix deposition and limiting protease activity in the vessel wall." (PMID 24312398, 2013). "Similar to cardiovascular pathologies observed in Marfan syndrome, medial layers of the aortas of smooth muscle Lrp1-deficient mice show extensive abnormalities including fragmentation, disorganization and loss of elastic laminae and accumulation of matrix proteins." (PMID 24312398, 2013). "Three new variants, including 1 deletion in DSC2, 1 missense SNPs in LRP1, and 1 nonsense SNP in FBN1 were confirmed to exist only in Marfan syndrome patients." (PMID 24484584, 2014). "Two new variants, including one nonsense SNP in the Marfan syndrome gene FBN1 and one missense mutation in exon 15 of LRP1, which may be related to the phenotype of the patients were identified." (PMID 24484584, 2014). "Marfan syndrome-like phenotypes such as tortuous aortas, disrupted elastic layers and abnormally activated transforming growth factor β (TGFβ) signaling are present in smooth muscle-specific LRP1 knockout (smLRP1−/−) mice." (PMID 19742316, 2009). "Suppression of PI3K activation by PDGFRβ prevents the Marfan-like phenotypic changes in the vascular wall in the presence of unabated TGFβ signaling, suggesting a pivotal role of LRP1-controlled and PDGFRβ-dependent PI3K activation in the pathogenesis of Marfan syndrome." (PMID 19742316, 2009). "TGFβ signaling is abnormally elevated in the absence of LRP1 in vivo, where analysis of SMC-specific LRP1 knockout (smLRP1−/−) mice revealed a Marfan syndrome-like phenotype with nuclear accumulation of phosphorylated Smad2 (p-Smad2) and disruption of elastic layers in the vessel wall." (PMID 19742316, 2009).
pancreatic ductal adenocarcinoma (5 papers, 2018 to 2023). An infiltrating adenocarcinoma that arises from the epithelial cells of the pancreas. "In pancreatic ductal adenocarcinoma (PDA) cells in vitro, loss of ANXA6 in CAF altered the development of ANXA6, LRP1, and TSP1 complexes, suppressing PDA and metastasis." (PMID 37124542, 2023). "The proteomic stromal signature of pancreatic ductal adenocarcinoma (PDA) shows a contribution of the annexin A6/LDL receptor-related protein 1/thrombospondin 1 (ANXA6/LRP1/TSP1) complex in tumour cell crosstalk." (PMID 29462943, 2018).
schizophrenia (5 papers, 2013 to 2023). A major psychotic disorder characterized by abnormalities in the perception or expression of reality. "In addition, the MACF1 gene is enriched significantly within brain specific critical exons, and the LRP1 gene ranked top 20 in list of schizophrenia-associated loci in the recent large-scale GWAS2." (PMID 26666178, 2015). "On the top of the list, both LRP1 and MACF1 genes are supported by 5 out of 6 independent evidences, suggesting their high pathogenic potential for schizophrenia." (PMID 26666178, 2015). "Of 8 genes showing more than two supporting evidences for pathogenic prediction, some of genes (e.g. LRP1, MACF1, DICER1 and ABCA2) harbours de novo mutations provided promising evidence as a strong candidate genes for schizophrenia." (PMID 26666178, 2015). "LRP1 is associated with high-functioning ASD and is also a susceptibility gene for schizophrenia." (PMID 36768688, 2023).
thyroid cancer (5 papers, 2017 to 2022). "We recently evidenced that the association of β1 integrin with domain II and IV of LRP-1 extracellular α-chain in thyroid carcinoma cells exerted a crucial function in routing it in a Rab11 endocytic recycling traffic." (PMID 36052226, 2022). "In conclusion, we identified an additional and innovative intracellular mechanism which demonstrates LRP-1 pro-motile action in thyroid cancer cells." (PMID 36052226, 2022). "In conclusion, we showed by three independent biochemical assessments that LRP-1 silencing leads to a significant induction of intracellular calpain activity in thyroid carcinoma cells." (PMID 36052226, 2022). "The molecular link between LRP-1, calpain activity and β1 integrin stability at cell surface of migrating thyroid carcinoma cells that we established in this study shed new light on the inner control of integrin activity by LRP-1." (PMID 36052226, 2022). "In the present study, we identified for the first time the regulation of calpain activity as a new mechanism by which LRP-1 controls the spreading and migratory capacities of thyroid carcinoma cells." (PMID 36052226, 2022). "Together, those data illustrated that the pro-invasive action of LRP-1 in thyroid carcinoma cells relies in part on the maintenance of a low level of calpain activity leading to a moderate cell-matrix interactions strength." (PMID 36052226, 2022). "Our data indicated that PKA helped to limit calpain activity in a LRP-1-dependent manner in the frame of cell-matrix interactions established by thyroid carcinoma cells." (PMID 36052226, 2022). "Noticeably, we recently described that LRP-1 contributes to thyroid carcinoma cell invasion by subtly controlling the composition and turn-over of adhesive complex." (PMID 36052226, 2022). "Altogether, these data showed that LRP-1-mediated control of calpain activity determined cell surface distribution of β1 integrins in thyroid carcinoma cells." (PMID 36052226, 2022). "Our data illustrated that during the attachment of FTC133 cells to gelatin, calpains inhibition by LRP-1 sustained the polarization of thyroid carcinoma cells and constituted a limiting mechanism in focal adhesion maturation." (PMID 36052226, 2022). "As Lrp1 was recently identified as a receptor for β1 integrins also in thyroid cancer cells, Lrp1 and integrins emerge as potential candidate genes for preventing cancer invasiveness." (PMID 30931303, 2019). "Overall, we identified an original molecular process in which LRP-1 acts as a main regulator of β1-integrin internalization and recycling in thyroid cancer cells." (PMID 29108253, 2017). "In thyroid cancer cells, the LRP-1/β1-integrin biomolecular complex was rather observed at the migration front and along the cell body where retraction fibers occur." (PMID 29108253, 2017). "In this study, we highlighted that the endocytic receptor LRP-1 establishes tight molecular connections with β1-integrin isoform at the cell surface of thyroid carcinoma cells." (PMID 29108253, 2017). "Having established that a LRP-1/β1-integrin complex occurs markedly at the plasma membrane of thyroid carcinoma cells, we analyzed the cellular distribution of these proteins using confocal immunofluorescence microscopy." (PMID 29108253, 2017). "Our data obtained from thyroid carcinoma cells clearly demonstrate that inhibition of LRP-1-dependent endocytosis by either RAP or RNA interference promotes a similar cell surface accumulation of both β1- and β2-integrin." (PMID 29108253, 2017). "To better understand how LRP-1 coordinates cell-extracellular matrix interface, we explored its ability to regulate cell surface integrins in thyroid carcinomas." (PMID 29108253, 2017). "In this study we pursued our investigation on LRP-1-dependent intracellular signals sustaining cell-matrix interactions dynamics by testing its contribution to calpain activity control in the context of thyroid carcinoma." (PMID 36052226, 2022).
thyroid cancer (continued). "To achieve this goal, we used a validated method of invalidation of LRP-1 in FTC-133 thyroid carcinoma cells by siRNA leading to a 70% decrease of its gene expression as evaluated by RT-qPCR, and to a 66% decrease of its protein expression measured by western blot." (PMID 36052226, 2022). "We demonstrated that PKA activity was decreased upon LRP-1 repression in thyroid carcinoma cells." (PMID 36052226, 2022). "In this study, we evidenced that calpain activity are dampened by LRP-1 in thyroid carcinoma cells." (PMID 36052226, 2022). "We demonstrated that LRP-1 and β1-integrin closely colocalized in thyroid carcinomas, and we thus investigated whether LRP-1 may contribute to β1-integrin intracellular trafficking." (PMID 29108253, 2017). "We observed that the cell-surface accumulation of β1 integrin upon LRP-1 silencing was partially reversed by calpain inhibition and that the occurrence of the cleaved form of talin appeared to follow the presence of this integrin at the membrane of thyroid carcinoma cells." (PMID 36052226, 2022). "Interestingly, results from immunoprecipitation assays carried out in various tumor and non-tumor cells indicated that the LRP-1/β1-integrin complex is not specific of thyroid carcinoma and likewise exists in many cellular environments." (PMID 29108253, 2017). "Interestingly, the formation of this complex is not specific of thyroid carcinoma and occurs in many tumor and non-tumor cells, probably depending at least to the amount and localization of LRP-1 at the cell surface." (PMID 29108253, 2017).
acute aortic dissection (4 papers, 2017 to 2023). "In a genome-wide association study analyzing genotypes of 753 individuals with sporadic aortic dissection, genetic variation within the low-density lipoprotein receptor-related protein 1 (LRP1) was associated with TAAD development." (PMID 35050224, 2022).
Autoimmunity (4 papers, 2015 to 2019). The occurrence of an immune reaction against the organism's own cells or tissues. "Among those, the LRP1/STAT6 novel mutation has the strongest case for being categorised as potentially causative of MAS given the presence of intriguing patterns of functional interaction with other major genes shaping autoimmunity." (PMID 26031516, 2015). "Thus, based on our results, these genes (in particular LRP1) should be considered as strong candidates for conferring risk to autoimmunity." (PMID 26031516, 2015). "Thus, impaired LRP1 action could ultimately cause autoimmunity." (PMID 26031516, 2015). "Of added interest, an autoimmunity pathway is present in Panel I with proteins LRP1 and POLA1." (PMID 31026304, 2019). "This function of LRP1 might explain why its removal in the microglial compartment is detrimental during CNS autoimmunity." (PMID 27400748, 2016). "There are other lines of evidence suggesting that LRP1 has anti-inflammatory roles, which indirectly could also aid in the prevention of autoimmunity." (PMID 26031516, 2015). "In summary, the involvement of LRP1 in the removal of cellular debris might constitute a key step in preventing autoimmunity." (PMID 26031516, 2015). "LRP1/STAT6 disclosed the strongest plausibility for autoimmunity." (PMID 26031516, 2015). "In addition to the genes above, it is also clear that this approach identified well known genes associated with autoimmunity within the exome variant data of these patients, which in this case are ICA1 and STAT6 (encoded by the same variant as LRP1)." (PMID 26031516, 2015). "Like in panel, I autoimmunity appears to be in play with proteins AFF3, SMYD3, and LRP1." (PMID 31026304, 2019).
breast tumor (4 papers, 2011 to 2020). "In human breast tumors, fibroblasts are the most abundant stromal cells and high levels of LRP1 expression was reported." (PMID 32850302, 2020). "Secreted Cath-D enhances proteolysis in the breast tumor microenvironment by degrading the cysteine cathepsin inhibitor cystatin C and promotes mammary fibroblast outgrowth by binding to LDL receptor-related protein-1 (LRP1)." (PMID 26183398, 2015). "Recently, studies also suggest that pro-cat-D secreted by epithelial cancer cells promotes fibroblast outgrowth in a paracrine LRP1-dependent manner in the breast tumor microenvironment." (PMID 21777416, 2011). "Interestingly and during epithelial-to-mesenchymal transition in breast tumors, LRP1 expression was derepressed through ZEB-1-dependent inhibition of LRP1-targeting miRNAs, thereby contributing to vascular mimicry of breast tumor cells." (PMID 32850302, 2020).
chondrosarcoma (4 papers, 2014 to 2023). A malignant cartilaginous matrix-producing mesenchymal neoplasm arising from the bone and soft tissue. "This is in line with our previous finding that N-TIMP-3 is endocytosed by chondrosarcoma cells in an LRP-1-dependent manner with similar kinetics to that of TIMP-317." (PMID 32694578, 2020). "We previously showed that the rate of TIMP-3 endocytosis by LRP1 can be quantified by adding purified FLAG-tagged recombinant TIMP-3 (1 nM) to HTB94 chondrosarcoma cells and monitoring its disappearance from the medium." (PMID 28798097, 2017). "We demonstrated that this mode of binding is able to support biologically relevant bridging of the MMP to LRP-1, as TIMP-3 was able to promote MMP-1 endocytosis by HTB94 chondrosarcoma cells." (PMID 32694578, 2020). "However, this mode of binding appears to be insufficient to support bridging to LRP-1 in a complex biological environment, as we found that neither TIMP-1 nor TIMP-2 could increase the rate of MMP-1 endocytosis by HTB94 chondrosarcoma cells." (PMID 32694578, 2020).
clear cell renal cell carcinoma (4 papers, 2017 to 2024). "Overexpression of LRP1 is associated with worsened prognosis and suppressive tumor immunity in renal clear-cell carcinoma." (PMID 31164891, 2019). "Consistently, LRP1 has been related to the poor prognosis of clear-cell renal cell carcinoma." (PMID 34819038, 2021). "Our analysis identified correlations between LRP1 and LRP2 mRNA expression levels and patient survival, but only in bladder urothelial carcinoma and renal clear cell carcinoma, respectively." (PMID 29088295, 2017).
colon adenocarcinoma (4 papers, 2018 to 2023). "Previous studies based on few colon adenocarcinoma samples have shown a frequent loss of LRP-1 immunohistochemical expression in adenocarcinomatous cells." (PMID 32582700, 2020). "Previous studies on few colon adenocarcinomas samples showed a frequent loss of LRP1 immunohistochemical expression in adenocarcinomatous cells." (PMID 29507659, 2018). "As a matter of fact, low expression of LRP1 in colon adenocarcinomas is associated with MSI." (PMID 35814400, 2022). "We have recently highlighted that low LRP-1 immunohistochemistry score in malignant colon adenocarcinoma cells is a strong prognosis marker." (PMID 32582700, 2020). "LRP1 mRNA levels were significantly lower in colon adenocarcinoma cells compared with colon mucosa and stromal cells obtained after laser capture microdissection." (PMID 29507659, 2018). "In summary, our study show that low LRP1 IHC expression in malignant colon adenocarcinoma cells is a strong prognosis predicator, especially in metastatic patients, in which it predicts a shorter OS in patients treated by anti-VEGF therapies." (PMID 29507659, 2018). "LRP1 mRNA expression was determined in colon adenocarcinoma and paired colon mucosa samples, as well as in stromal and tumor cells obtained after laser capture microdissection." (PMID 29507659, 2018). "A recent clinical study from our team demonstrated that LRP-1 expression was significantly lower in colon adenocarcinoma cells compared to colon epithelial cells and stromal cells and that this decrease in LRP-1 expression is associated with worse patient outcomes." (PMID 32582700, 2020).
osteoporosis (4 papers, 2012 to 2025). A condition of reduced bone mass, with decreased cortical thickness and a decrease in the number and size of the trabeculae of cancellous bone (but normal chemical composition), resulting in increased fracture incidence. "Here, we analyze the function of Lrp1 in osteoblasts in vivo by genetic means and demonstrate that osteoblast Lrp1 protects against osteoporosis by limiting a novel PDGF–RANKL signaling axis in osteoblast-to-osteoclast communication." (PMID 29507818, 2018). "Mice in which osteoblasts lack Lrp1 show osteoporosis due to highly increased osteoclast numbers and bone resorption." (PMID 30518764, 2018). "Investigations into the mechanisms underpinning formation of severe and persistent defects in skeletal elements caused by LRP1 loss are an essential for understanding the fundamental processes of morphogenesis, as well as the emergence of skeletal pathologies including DDH, osteoporosis and OA." (PMID 39865089, 2025). "Taken together, these data support the concept that loss of Lrp1 in osteoblasts leads to increased osteoblast PDGF signaling, which in turn stimulates Tnfsf11 expression and thereby increases osteoclast numbers and activity, resulting in severe osteoporosis of all bone compartments in mice." (PMID 29507818, 2018). "Mice lacking Lrp1 specifically in the osteoblast lineage displayed normal osteoblast function but severe osteoporosis due to highly increased osteoclast numbers and bone resorption." (PMID 29507818, 2018).